PPARD (peroxisome proliferator activated receptor delta)
Diseases named in the same sentence as PPARD in open-access papers (continued):
Sharing a sentence is not in itself a finding about the gene and the disease.
endometriosis (1 paper, 2025). The growth of functional endometrial tissue in anatomic sites outside the uterine body. "SSTR5, KCNH2, CASP3, PTGER1, PPARD, and TYMP emerged as the top-ranked targets, indicating their potential significance in the treatment of endometriosis." (PMID 39754173, 2025).
gestational diabetes (1 paper, 2022). Carbohydrate intolerance first diagnosed during pregnancy. "Furthermore, one of the clock genes, “PPARD”, expressed abnormally to the patients with gestational diabetes mellitus (GDM) and T2DM pregnant women." (PMID 35207564, 2022).
intrauterine growth restriction (1 paper, 2018). "In another study, rats with intrauterine growth restriction have high expressions of miR-29a, which has a direct interaction with its target gene, peroxisome proliferator-activated receptor δ (PPARδ), and PPARδ's coactivator, peroxisome proliferator-activated receptor- γ coactivator-1 α (PGC-1 α)." (PMID 30648107, 2018).
latent infection (1 paper, 2025). "Polymorphisms like rs1761667 that lower CD36 expression could thus alter PPARδ-driven lipid–immune crosstalk, affecting the host’s ability to control latent infection." (PMID 41410218, 2025).
lupus nephritis (1 paper, 2021). Glomerulonephritis in the context of systemic lupus erythematosus. "Activation of PPARδ by PPARδ agonists in human umbilical cord vein cells (HUVECs) was found to attenuate ER stress induced by the plasma from patients with lupus nephritis." (PMID 34947939, 2021). "Activation of PPARδ by PPARδ agonists in human umbilical cord vein cells (HUVECs) attenuated ER stress induced by the plasma from patients with lupus nephritis." (PMID 34947939, 2021).
lymphoma (1 paper, 2017). A malignant (clonal) proliferation of B- lymphocytes or T- lymphocytes which involves the lymph nodes, bone marrow and/or extranodal sites. "The signaling effects of LDLs were not seen in normal lymphocytes or glycolytic lymphoma cell-lines but were restored by transduction with the nuclear receptor PPARδ, which mediates metabolic activity in CLL cells." (PMID 27932296, 2017).
mastitis (1 paper, 2024). Inflammation of breast tissue during lactation or postpartum due to an obstructed duct or infection. "Based on Western blotting in the present research, the mammary glands with subclinical bovine mastitis exhibited obviously increased PPARα expressions but reduced PPARδ/β and PPARγ expressions, in contrast to the healthy mammary glands." (PMID 39765775, 2024).
mental disorder (1 paper, 2022). A disease that has its basis in the disruption of mental process. "Similarly, PPARγ and PPARδ have well-described roles in the regulation of mitochondrial function and PPAR-γ has even been investigated as a therapeutic target for mental disorders in this regard." (PMID 35941107, 2022).
metastatic colorectal cancer (1 paper, 2023). "Moreover, we were able to demonstrate the direct impact of CCAT1, CCAT2, and MYC on metastatic colorectal cancer cell migration by affecting targets of Wnt signaling, including the upregulation of PPARD." (PMID 37347737, 2023).
mismatch repair deficiency (1 paper, 2006). "In contrast with the previously observed acceleration of intestinal neoplasia in the context of the ApcMin/+ mouse, PPARδ deficiency does not alter the phenotype of mismatch repair deficiency." (PMID 16672050, 2006).
periapical granuloma (1 paper, 2021). Chronic nonsuppurative inflammation of periapical tissue resulting from irritation following pulp disease or endodontic treatment. "In the periapical granuloma, PPARD gene was the highest alternative allele prediction from G>C (rs9794) with 1.0 polymorphism percentage in other African populations followed by TSHR with a polymorphism percentage of 0.94 from G>C (rs1991517) in the same population." (PMID 34539639, 2021). "In our study, datasets of the identified active genes revealed that periapical granulomas have the highest correlation with SNPs for PPARD, TSHR, and SLC16A1 in the African population." (PMID 34539639, 2021).
Renal atrophy (1 paper, 2013). Atrophy of the kidney. "Our data demonstrate that renal atrophy induced by experimental RAS can be inhibited by the pharmacological activation of PPARδ by its agonist, HPP593." (PMID 23691217, 2013).
Salmonella Infections (1 paper, 2021). Infections with bacteria of the genus SALMONELLA. "We next proposed the role of PPARδ in Salmonella infection in greater detail." (PMID 34696686, 2021). "Apart from PPARδ, the work identifies new targets of KDM6B demethylase activity in the host upon Salmonella infection such as CSNK1D and DAAM1." (PMID 34696686, 2021). "While, si-RNA-mediated KDM6B knockdown or GSKJ4 treatment of cells showed reduced or no up regulation of PPARδ upon 18 h post Salmonella infection." (PMID 34696686, 2021). "However, we do not see a further increase in PPARδ upon Salmonella infection along with drug treatment in comparison to drug-treated control cells." (PMID 34696686, 2021).
sarcoidosis (1 paper, 2015). Sarcoidosis is a multisystemic disorder of unknown cause characterized by the formation of immune granulomas in involved organs. "We found that PPARβ/δ mRNA expression is higher in total BAL cells in non-LS patients compared to LS patients and HC, and a tendency towards higher PPARδ protein expression in blood CD4+ and CD8+ T cells in sarcoidosis patients." (PMID 25969669, 2015).
thyroid cancer (1 paper, 2009). "Moreover, PPARδ is upregulatedin human thyroid tumors and the deregulation of the PPARδ/cyclin E1 pathway maybe important not only in thyroid cancer but also in other types of carcinomas." (PMID 19325917, 2009).
tuberculosis (1 paper, 2024). A chronic, recurrent infection caused by the bacterium Mycobacterium tuberculosis. "In this study, we report a significant role for PPARδ in exacerbation of lipid accumulation and inflammation in in vitro and ex vivo models of tuberculosis." (PMID 38989454, 2024).
VLCAD deficiency (1 paper, 2022). "In summary, our results confirm that the PPARδ agonist REN001 is a potential treatment for VLCAD deficiency, exhibiting a positive effect on enzyme activity and cellular bioenergetics." (PMID 36078043, 2022).
tumor (204 papers, 2005 to 2026). "In lung cancer, PPARD overexpression is linked to poor prognosis, though its role remains ambiguous, with studies indicating both tumor-promoting and inhibitory effects." (PMID 39922804, 2025). "Mild mitochondrial inhibition induced by low-dose etomoxir or signals from tumor-associated macrophages altered the lipidome and triggered the downstream transcriptional program of PPARδ." (PMID 40607925, 2025). "Whereas it has occasionally been associated with tumor suppression, increased PPARD expression has predominantly been linked to enhanced metastasis in several in vivo models." (PMID 40607925, 2025). "The activation or heightened expression of PPARδ has been increasingly recognized as playing a pivotal role in cell proliferation and tumor growth, with numerous studies substantiating this association." (PMID 39156976, 2024). "The involvement of PPARδ in these diverse mechanisms not only underlines its importance in tumor progression but also highlights its potential as a promising target for therapeutic interventions aimed at combating cancer." (PMID 39156976, 2024). "PPARδ increased Ccl20 level to chemoattract Ccr6+ immunosuppressive cells, including tumor-associated macrophages, myeloid-derived suppressor cells and T regulatory cells, but decreased CD8+ T cells in gastric tissues." (PMID 37572185, 2023). "These contradictory findings suggest that PPARδ differentially affects tumour-associated functions depending on the cell type, cellular context, stage of differentiation, and the environment of soluble mediators." (PMID 33637678, 2021). "It is suggested that PPARδ plays different roles depending on the site of its expression: in normal cells in the tumour microenvironment it causes promotion of tumourigenesis, while in cancer cells – its suppression." (PMID 34921177, 2021). "One possible explanation is that tumor suppressor loss alters PPARD-driven transcriptional regulation." (PMID 29143738, 2017). "Deletion of PPARδ attenuated colonic inflammation and colitis-associated tumor development in animal experiments." (PMID 28852270, 2017). "Increasing literatures show that aberrant expression of PPARδ is associated with pro-inflammatory response and tumor progression." (PMID 28948004, 2017). "In contrast to classical growth factors such as EGF which stimulate proliferation of wild-type organoids, we found that PPARD activation is only sufficient to drive growth with concurrent tumor suppressor loss." (PMID 29143738, 2017). "As discussed in Section 2, PPARδ regulates the inflammatory Saa1/2/3 and S100a8/9 pathways, which in tumor-bearing mice are associated with MDSC expansion and metastasis." (PMID 28077942, 2016). "In patients with pancreaticcancer, PPARδ levels were correlated with advanced pathological tumor stage,increasing the risk of tumor recurrence and distant metastases." (PMID 18528523, 2008). "On the other hand, PPARδ has been linked to tumor development and progression." (PMID 37645246, 2023). "Importantly, immunotherapy with anti-CD40 or anti-PD1 antibody achieved a markedly improved outcome in tumor-bearing mice with PPARδ deficiency in B cells or treated with PPARδ inhibitor." (PMID 37291146, 2023). "PPARδ and miR-17 may be markers differentiating tumour tissue from surgical margin and miR-17 may have diagnostic role in NSCLC histotypes differentiation." (PMID 34921177, 2021). "However, obesity induces lipid accumulation driven by PPARα and PPARδ, which causes dysfunction of NK cell metabolism, reduced production of IFNγ, and reduced tumor cell killing." (PMID 34283042, 2021). "Alternatively, tumor suppressor loss may alter the cellular response to PPARD activation and/or provide complementary pro-tumorigenic signals." (PMID 29143738, 2017). "Lastly, PPARδ and fatty acid oxidation are required to maintain asymmetric stem cell division, an area that may be linked to ER+ tumor specification and one unexplored thus far in mammary tumorigenesis." (PMID 28077942, 2016).
tumor (continued). "PPARγ and PPARδ agonists represent unique classes of drugs that act through their ability to modulate gene transcription associated with intermediary metabolism, differentiation, tumor suppression, and in some instances proliferation and cell adhesion." (PMID 18566686, 2008). "In addition to theirmetabolic actions, an emerging area of investigation for PPARγ and PPARδ agonists is their ability to modulate mammary celllineage and genes associated with tumor suppressor function and cell fatedetermination." (PMID 18566686, 2008). "Thus, it remains to be seen whether tumor-associated myofibroblasts may be contributing to the increase in PPARD mRNA that was observed in the NMSCs." (PMID 39195246, 2024). "Contrary to some early reports, our findings align with growing evidence that PPARδ also promotes tumor progression and metastasis in PDAC." (PMID 40607925, 2025). "Inhibiting PPARD can disrupt these pathways, reduce tumor progression, and improve chemotherapy efficacy." (PMID 39922804, 2025). "In subcutaneous tumor samples of nude mice, the PPARD tendency was coincident with that in MB-231 cells (p < 0.05)." (PMID 39922804, 2025). "In vivo and in vitro experiments show that inhibiting glycolysis with DCA reduces tumor growth and induces apoptosis, further confirming the role of the H3K18la/PPARD/AKT axis in BC." (PMID 39922804, 2025). "Most of these specific mutations (n = 20; 80%) were exclusive to NAT, including those affecting key genes such as NOTCH1 (the most mutated gene), FAT1, or PPARD; while 20% were shared between NAT and tumor tissue, affecting genes such as CDKN2A." (PMID 40465458, 2025). "As a tumor-promoting effect, ligand-activated PPARD induced HCC cell proliferation and invasion through the pyruvate dehydrogenase kinase 1/protein kinase B (﻿AKT)/GSK3β signaling pathway." (PMID 39899669, 2025). "Focusing on specific PPAR pathway receptors, we observed PPARG and PPARD upregulation in PC tumor tissue samples in the TCGA cohort." (PMID 40860798, 2025). "PPARD mRNA expression was significantly elevated in GBM compared with non-tumor tissues in the Rembrandt cohort (Gene Expression Omnibus [GEO] accession GSE108476)." (PMID 40996961, 2025). "Inhibition of this pathway results in the activation of peroxisome proliferator-activated receptor D (PPARD), resulting in the dependence of tumor metabolism on fatty acid oxidation (FAO)." (PMID 40696413, 2025). "Conversely, the activation of PPARD leads to the development of a tumor suppressive TME by inhibiting Th2/M2 differentiation." (PMID 40860798, 2025). "Treatment of ApcMin/+ mice with the PPARδ agonist GW501516 reduced the activation of normal and tumor-associated intestinal CD8+ T cells and increased intestinal adenoma burden." (PMID 39292167, 2024). "PPARδ-mediated metabolic reprogramming in tumor cells led to the inhibition of anaerobic glycolysis and increased oxidative glutamine and lipid metabolism." (PMID 39451206, 2024). "In tumor samples, PPARD and PPARG were correlated with EMT-related pathways and proliferation-related pathways, respectively." (PMID 38529307, 2024). "APCs and NSAIDs inhibit the common target PPARδ, thus providing a link between the genetic alterations behind tumor development and cancer chemoprevention." (PMID 37251321, 2023). "The expression levels of ANGPTL4 and PPARD were notably higher in tumour tissue, whereas the expression levels of FABP1, SLC27A1 and OLR1 were elevated in normal tissue." (PMID 37556076, 2023). "PPARδ inactivation not only significantly reduced IL-10+ Bregs in naïve mice, but also prevented IL-10+ Breg induction by tumor and anti-CD40 engagement." (PMID 37291146, 2023). "The translation products of many genes activated by PPARδ possess immunosuppressive properties, resulting in low immune infiltration as well as high tumor burden." (PMID 37693904, 2023).
tumor (continued). "Genetic inactivation of PPARδ in B cells impaired the development and function of IL-10+ B cells, and treatment with PPARδ inhibitor diminished the induction of IL-10+ Bregs by tumor and CD40 engagement." (PMID 37291146, 2023). "In transgenic hepatitis B virus mice, long-term treatment with GW0742 reduced the number of liver tumor foci, based on a decrease in cyclin D1 and c-Myc expression, and activated PPARδ reduced the proliferation of tumor cells." (PMID 37251321, 2023). "Together, these results suggest that PPARδ plays a critical role in the development of tumor-induced immunosuppressive B cells (i.e., Bregs) that inhibit the antitumor effect of immunotherapy." (PMID 37291146, 2023). "As valid for PPARα, metabolic reprogramming of natural killer (NK) cells by administration of fatty acids or PPARδ agonists restricted anti-tumor responses in obese melanoma-bearing mice." (PMID 37833991, 2023). "Alternatively, dietary composition and specifically high fat diet has been reported to induce a peroxisome proliferator-activated receptor delta signature in intestinal stem cells and drive tumor formation." (PMID 36959559, 2023). "In the present study, we discovered that peroxisome proliferator-activated receptor delta (PPARδ) is highly expressed in IL-10-producing Bregs and serves as a key regulator controlling their development and function in tumor-bearing mice and cancer patients." (PMID 37291146, 2023). "Activation of PPARD has also been associated with the increased expression of both SOD1 and SOD2, which are linked with tumor progression and migration in AFG1-induced LA." (PMID 35342393, 2022). "The role of PPARδ as oncogenic factor or tumor suppressor factor is still controversial, which is influenced by tumor types and experimental methods." (PMID 35151320, 2022). "Taken together, the expression of PPARδ had a close correlation with several immune cells in HCC tumor microenvironment." (PMID 35151320, 2022). "In most of the reported literature, activation or high expression of PPARδ has been demonstrated to be related to cell proliferation and tumor growth." (PMID 35151320, 2022). "An important point is that we observed no changes in dynamic real-time metabolic conversion of pyruvate to lactate in hyperpolarized metabolic imaging despite noting measurable growth in tumor size from 10 to 35 weeks in PPARD mice." (PMID 35163565, 2022). "Tregs proliferating into the tumor microenvironment (TME) accumulate intracellular lipids under the intrinsic control of PPARδ." (PMID 35406621, 2022). "KAT2A and PPARD showed different expressions based on tumor stages and grades with favorable survival rates in patients." (PMID 36476410, 2022). "The expression level of PPARδ was elevated while the clinical staging and grading of tumor progressed." (PMID 35151320, 2022). "After accumulation of tumor cell-conditioned medium from HCT116 cells with knockdown of ERO1A, PPARδ and the both genes, the tumor cell-conditioned medium was mixed to that of HUVECs." (PMID 34712608, 2021). "Elevated PPARδ expression promotes fat oxidation near adipose tissue surrounding the tumor, thus providing a sufficient supply of energy substrates for the development and proliferation of the tumor microenvironment." (PMID 33673357, 2021). "Given this, further researches are still needed to unravel the effect of PPARδ on tumor angiogenesis." (PMID 34712608, 2021). "As expected, the tumor size was increased in PPARδ-knockdown mice when compared with that in control mice." (PMID 34712608, 2021). "The average tumor volume was significantly higher in PPARδ-knockdown mice than that in HCT116-NC mice." (PMID 34712608, 2021). "Next, to identify the effect of PPARδ on tumor angiogenesis, the tumor sections were stained for CD31, the microvessel marker." (PMID 34712608, 2021). "In SCC, a significant difference in the level of expression between tumour and control tissue was observed for PPARδ (p = 0.0003; Mann–Whitney U test)." (PMID 34921177, 2021).